ZNF668 (zinc finger protein 668)
Description:
May be involved in transcriptional regulation. May play a role in DNA repair process.
Synonyms: FLJ13479; NEDGEF
Tractability: PROTAC: UniProt records ubiquitination sites on it; ubiquitination databases record sites on it; its protein half-life has been measured.
Gene: Protein-coding gene on chromosome 16 (31,060,842 to 31,074,240, reverse strand). Ensembl gene ENSG00000167394.
Subcellular location: Nucleus
Subcellular location (Human Protein Atlas): Nucleoli; Nucleoli rim; Nucleoplasm
Pathways (Reactome):
Gene expression (Transcription): Generic Transcription Pathway
Gene Ontology:
Molecular function: transcription cis-regulatory region binding; DNA-binding transcription repressor activity, RNA polymerase II-specific; RNA polymerase II cis-regulatory region sequence-specific DNA binding
Biological process: DNA repair; regulation of transcription by RNA polymerase II; negative regulation of transcription by RNA polymerase II
Cellular component: nucleus
Genetic constraint (gnomAD): Loss-of-function variants: 10 observed, 37.07 expected, observed/expected ratio (o/e) 0.27, 90% interval 0.17 to 0.46. The upper end of that interval is the gene's LOEUF score, 0.46, which puts it in group 2 of 6, group 1 being the genes least tolerant of losing a copy. Missense variants: 745 observed, 877.33 expected, observed/expected ratio (o/e) 0.85, 90% interval 0.8 to 0.9. Synonymous variants: 423 observed, 380.69 expected, observed/expected ratio (o/e) 1.11, 90% interval 1.02 to 1.2.
Homologues: Orthologues: chimpanzee ZNF668 (100% identical), macaque ZNF668 (99% identical), pig ZNF668 (96% identical), dog ZNF668 (96% identical), rabbit ZNF668 (95% identical), mouse Zfp668 (92% identical), rat Zfp668 (92% identical), guinea pig ZNF668 (90% identical). Paralogues in human: ZNF850 (29% identical), PRDM5 (24% identical), ZNF358 (20% identical), ZNF579 (19% identical).
Diseases named in the same sentence as ZNF668 in open-access papers:
ZNF668 is named in the same sentence as 12 diseases in open-access papers, as found by Europe PMC text mining. Sharing a sentence is not in itself a finding about the gene and the disease. The quoted sentences say what the papers report.
breast carcinoma (4 papers, 2015 to 2025). "It was previously reported that the ZNF668 gene was mutated in 11.4% of breast cancers." (PMID 37240013, 2023). "Therefore, it is necessary to analyze the expression and gene mutation of ZNF668 in malignant tumors other than breast cancer." (PMID 37240013, 2023). "Among the 9 cancer types with proteomics data recorded in CPTAC, ZNF668 protein expression was significantly upregulated in 5 cancers: breast cancer, head and neck cell carcinoma, hepatocellular carcinoma, LUAD, and LUSC." (PMID 41614761, 2025). "The ZNF668 gene functions as a tumor suppressor gene in breast cancer." (PMID 37240013, 2023). "Moreover, ZNF668 knockdown inhibits DNA repair by homologous recombination in breast cancer cells." (PMID 37240013, 2023). "Therefore, ZNF668 may act as a tumor suppressor in bladder cancer, as well as in breast cancer." (PMID 37240013, 2023).
bladder cancer (2 papers, 2023 to 2025). "In conclusion, the decreased ZNF668 expression in bladder cancer was associated with submucosal and muscle invasion of cancer cells." (PMID 37240013, 2023). "Patients with low expression of ZNF668 protein in the nuclei of bladder cancer cells are at high risk for muscle invasion, which is a poor prognostic factor." (PMID 37240013, 2023). "We histologically analyzed ZNF668 protein expression in bladder cancer and examined mutations of the ZNF668 gene in 68 cases of bladder cancer." (PMID 37240013, 2023). "The decreased ZNF668 expression in bladder cancer was associated with submucosal and muscle invasion of cancer cells." (PMID 37240013, 2023). "Somatic mutations resulting in amino acid mutations in ZNF668 were found in 7.3% of the bladder cancer cases." (PMID 37240013, 2023). "In the histological analysis, the decreased ZNF668 protein expression in bladder cancer cell nuclei was associated with submucosal and muscle infiltration of bladder cancer." (PMID 37240013, 2023). "Decreased ZNF668 expression in bladder cancer was associated with submucosal and muscle invasion of cancer cells." (PMID 37240013, 2023). "Here, we histologically analyzed the production of ZNF668 protein via ZNF668 gene expression (hereinafter also referred to simply as “ZNF668 protein expression”) in bladder cancer and examined mutations of the ZNF668 gene in bladder cancer tissue." (PMID 37240013, 2023). "While the oncogenic role aligns with reports of ZNF668 promoting proliferation in leukemia cells, it contradicts studies where ZNF668 acts as a potent inhibitor of migration and invasion in lung and bladder cancer cells." (PMID 41614761, 2025). "In bladder cancer with submucosal infiltration, the expression of the ZNF668 protein evaluated by IRS was significantly lower than that without submucosal infiltration." (PMID 37240013, 2023). "In bladder cancer with muscle invasion, the expression of ZNF668 protein evaluated by IRS was significantly lower than that without muscle invasion." (PMID 37240013, 2023). "In bladder cancer, the ZNF668 protein was expressed in the nuclei of cancer cells, but in a few cases, it was also expressed in the cytoplasm." (PMID 37240013, 2023). "In bladder cancer, the ZNF668 protein was expressed in the nuclei of cancer cells." (PMID 37240013, 2023). "Assuming that the ZNF668 is involved in the DNA repair, the decreased expression of the ZNF668 protein in the nuclei of bladder cancer cells may contribute to cancer progression." (PMID 37240013, 2023). "However, the rate of somatic mutations in the exons of the ZNF668 gene in bladder cancer was not high (7.3%)." (PMID 37240013, 2023). "In bladder cancer with submucosal and muscular infiltration, the expression of ZNF668 protein was significantly lower than that without submucosal and muscular infiltration." (PMID 37240013, 2023).
leukemia (2 papers, 2025). A malignant (clonal) hematologic disorder, involving hematopoietic stem cells and characterized by the presence of primitive or atypical myeloid or lymphoid cells in the bone marrow and the blood. "It is suggested that the high ZNF668 expression could promote cancer cell proliferation and migration for leukemia." (PMID 40699783, 2025). "A half of these proteins have no reported relationship with leukemia, i.e., LTB4R2, DDX39B, ZNF668, ZNF788, and DXO." (PMID 40699783, 2025).
acute myeloid leukemia (1 paper, 2025). Acute myeloid leukemia (AML) is a group of neoplasms arising from precursor cells committed to the myeloid cell-line differentiation. "We found that zinc finger protein 668 (ZNF668), eosinophil granule ontogeny transcript (EGOT), and glutamate metabotropic receptor 7 (GRM7) could serve as novel biomarkers for acute myeloid leukemia (LMAL)." (PMID 40699783, 2025).
carcinoma in situ (1 paper, 2023). "Therefore, the association between ZNF668 and carcinoma in situ cannot be examined in this study." (PMID 37240013, 2023).
superficial spreading melanoma (1 paper, 2016). A type of melanoma that typically occurs in light-skinned individuals ranging in age from young adults to the elderly. "Superficial spreading melanoma (SSM) and nodular melanoma (NM characteristically express the eight genes GALNT7, DIS3, FGFR1OP, G3BP2, MTAP, SEC23IP, USO1, and ZNF668." (PMID 27322213, 2016).
cancer (5 papers, 2015 to 2025). A tumor composed of atypical neoplastic, often pleomorphic cells that invade other tissues. "To evaluate the utility of ZNF668 as a potential pan-cancer diagnostic biomarker, we performed ROC curve analysis of its expression levels." (PMID 41614761, 2025). "In contrast to the widespread positive associations, the correlation of ZNF668 with a subset of immune genes was heterogeneous, varying significantly between different cancer types." (PMID 41614761, 2025). "The results demonstrated that ZNF668 exhibited high accuracy in distinguishing tumor tissues from normal tissues, showing excellent diagnostic performance in 13 different cancer types with an AUC greater than 0.7." (PMID 41614761, 2025). "The reason why the down-regulation of ZNF668 is associated with cancer invasiveness remains uncertain." (PMID 37240013, 2023). "Conversely, ZNF668 expression was significantly downregulated in 3 cancer types: KICH, KIRP, and THCA (p < 0.05)." (PMID 41614761, 2025). "We first established the clinical relevance of ZNF668 by analyzing its expression and prognostic value across a wide range of human cancers." (PMID 41614761, 2025). "We found that ZNF668 expression exhibited a consistent positive correlation with MSI across cancers." (PMID 41614761, 2025). "In paired samples, ZNF668 mRNA expression was significantly upregulated in 7 cancer types: BRCA, ESCA, HNSC, KIRC, LIHC, LUAD, and STAD, while it remained significantly downregulated in KICH, PRAD, and THCA." (PMID 41614761, 2025). "Our pan-cancer analysis identifies ZNF668 as a frequently overexpressed gene with significant diagnostic and prognostic value." (PMID 41614761, 2025). "While the ZFP family has been extensively researched, the specific role of its member, ZNF668, in cancer remains largely uncharacterized." (PMID 41614761, 2025). "This study provides a comprehensive pan-cancer analysis of ZNF668, investigating its expression patterns, prognostic value, genomic alterations, functional pathways, and its complex interplay with the tumor immune microenvironment." (PMID 41614761, 2025). "Specifically, high ZNF668 expression predicted a poorer OS in 5 cancer types: KIRC, KIRP, LIHC, THCA, and UVM, whereas it was associated with a better OS in ESCA and THYM." (PMID 41614761, 2025). "In contrast, ZNF668 expression was generally lower in various cancer cell lines of epithelial origin, with the lowest levels observed in HNSC, ESCA, and KIRC." (PMID 41614761, 2025). "This study presents a comprehensive pan-cancer analysis of ZNF668, investigating its expression profiles, genetic alterations, functional pathways, association with immune infiltration, and clinical correlations across cancer types from TCGA." (PMID 41614761, 2025). "In the PFI analysis, high ZNF668 expression predicted a poorer prognosis for 5 cancer types: KIRC, KIRP, LIHC, PRAD, and UVM, while it was associated with a better prognosis in OV." (PMID 41614761, 2025). "ZNF668 mRNA expression was analyzed across a wide range of cancer cell lines using the CCLE database." (PMID 41614761, 2025). "Collectively, this comprehensive analysis aims to elucidate the multifaceted role of ZNF668 across various cancers, providing foundational insights into its potential as a prognostic indicator and its relevance in the tumor immune microenvironment." (PMID 41614761, 2025). "Analysis of the cBioPortal pan-cancer cohort revealed that ZNF668 is genetically altered in 1.9% of all tumors." (PMID 41614761, 2025). "ZNF668 expression exhibited a remarkably consistent positive correlation with a large number of immune regulatory genes across diverse cancer types." (PMID 41614761, 2025). "TCGA pan-cancer analysis indicated that ZNF668 is generally highly expressed in the majority of cancer types." (PMID 41614761, 2025).
cancer (continued). "In terms of DSS, high ZNF668 expression indicated a poor prognosis in 6 cancer types: BRCA, KIRC, KIRP, LIHC, THCA, and UVM, but predicted a better prognosis in DLBC and ESCA." (PMID 41614761, 2025). "ZNF668 (2 sites) is a zinc finger protein whose role in DNA repair, cell proliferation and cancer has been investigated." (PMID 29047347, 2017). "For CNVs, both amplifications and deletions of ZNF668 were observed in most cancer types." (PMID 41614761, 2025). "ZNF668 expression broadly correlated with immune cell infiltration across various cancers." (PMID 41614761, 2025). "Therefore, this study undertakes a comprehensive pan-cancer analysis to elucidate the functions of ZNF668." (PMID 41614761, 2025). "We further examined the pan-cancer genetic alterations of ZNF668." (PMID 41614761, 2025). "Furthermore, in the majority of cancer types, a positive correlation was found between ZNF668 CNV and its mRNA expression." (PMID 41614761, 2025). "Similar to a previous report, we observed ZNF668 expression in the cytoplasm of cancer cells in a small number of cases, but its significance is unknown at this time." (PMID 37240013, 2023). "Further analysis revealed a strong and consistent positive correlation between ZNF668 expression levels and CAF abundance in the vast majority of analyzed cancer types, such as PAAD, READ, and BRCA." (PMID 41614761, 2025). "Meanwhile, some proteins act as known oncogenes in most cancers except LAML, such as ZNF668 and GRM7." (PMID 40699783, 2025). "Our findings revealed varying correlations between ZNF668 expression and TMB across different cancer types." (PMID 41614761, 2025). "Similarly, ZNF668 was positively correlated with PVRL2 (Nectin-2), CD276 (B7-H3), TGFB1, and multiple members of the TNF receptor superfamily, including TNFRSF4 (OX40), TNFRSF18 (GITR), and TNFRSF25, in the vast majority of analyzed cancers." (PMID 41614761, 2025).
tumor (4 papers, 2022 to 2025). "The discrepant associations observed across different tumor types underscore the context-dependent functionality of ZNF668, warranting further investigation to delineate its specific mechanistic roles." (PMID 41614761, 2025). "If ZNF668 acts as a tumor suppressor, it is assumed that the occurrence of multiple somatic mutations in trans will lead to tumor growth." (PMID 37240013, 2023). "This raises the question of why ZNF668 functions as a tumor suppressor in isolated epithelial cancer cells but correlates with poor prognosis in patient tumors of the same origin." (PMID 41614761, 2025). "Our study provides a new framework for restoring effective anti-tumor immunity by targeting ZNF668 to dismantle the immunosuppressive TME." (PMID 41614761, 2025). "Further investigation of the relationship between ZNF668 and tumor suppression is needed in future studies." (PMID 37240013, 2023). "Among all screened agents, Dasatinib exhibited the strongest negative correlation with ZNF668 expression (rho= −0.441, p < 0.05), suggesting a hypothesis that Dasatinib might exert its effects by potentially interacting with ZNF668 for anti-tumor effects." (PMID 41614761, 2025). "Therefore, ZNF668 and ZNF788 should be favored by tumor biologists, especially in LAML-related researchers." (PMID 40699783, 2025). "The functions of BCDIN3D, ZNF668, and GNPTG in tumor are poorly studied." (PMID 36470859, 2022).
ZNF668 also shares sentences with these, for which no sentence is quoted: bladder tumors (1 paper); breast tumor (1); hepatocellular carcinoma (1); non-small cell lung carcinoma (1).